ZNF603P (zinc finger protein 603, pseudogene)
Synonyms: p373c6.7
Gene: Unprocessed pseudogene on chromosome 6 (28,176,188 to 28,176,674, forward strand). Ensembl gene ENSG00000216901.
Diseases named in the same sentence as ZNF603P in open-access papers:
ZNF603P is named in the same sentence as 1 disease in open-access papers, as found by Europe PMC text mining. Sharing a sentence is not in itself a finding about the gene and the disease.
ZNF603P shares sentences with these, for which no sentence is quoted: schizophrenia (1 paper).